NKAIN4 (sodium/potassium transporting ATPase interacting 4)
Synonyms: C20orf58; FAM77A; bA261N11.2
Tractability: Antibody: UniProt places it where antibodies can reach, with high confidence; UniProt predicts a signal peptide or a membrane-spanning region; its Gene Ontology location is reachable by antibodies, with medium confidence.
Gene: Protein-coding gene on chromosome 20 (63,240,784 to 63,272,694, reverse strand). Ensembl gene ENSG00000101198.
Subcellular location: Cell membrane
Gene Ontology:
Molecular function: protein binding
Biological process: regulation of sodium ion transport
Cellular component: membrane; plasma membrane
Genetic constraint (gnomAD): Loss-of-function variants: 25 observed, 24.2 expected, observed/expected ratio (o/e) 1.03, 90% interval 0.75 to 1.44. The upper end of that interval is the gene's LOEUF score, 1.44, which puts it in group 5 of 6, group 1 being the genes least tolerant of losing a copy. Missense variants: 283 observed, 251.33 expected, observed/expected ratio (o/e) 1.13, 90% interval 1.02 to 1.24. Synonymous variants: 122 observed, 104.56 expected, observed/expected ratio (o/e) 1.17, 90% interval 1.01 to 1.36.
Homologues: Orthologues: chimpanzee NKAIN4 (97% identical), macaque NKAIN4 (88% identical), mouse Nkain4 (83% identical), dog NKAIN4 (79% identical), guinea pig NKAIN4 (77% identical), rat Nkain4 (76% identical), pig NKAIN4 (73% identical), zebrafish nkain4 (69% identical), tropical clawed frog nkain4 (68% identical), Drosophila melanogaster NKAIN (43% identical), Caenorhabditis elegans gldi-7 (31% identical). Paralogues in human: NKAIN3 (59% identical), NKAIN2 (59% identical), NKAIN1 (57% identical).
Diseases named in the same sentence as NKAIN4 in open-access papers:
NKAIN4 is named in the same sentence as 7 diseases in open-access papers, as found by Europe PMC text mining. Sharing a sentence is not in itself a finding about the gene and the disease. The quoted sentences say what the papers report.
esophageal cancer (1 paper, 2022). A primary or metastatic malignant neoplasm involving the esophagus. "Using the pro-metastasis esophageal cancer cell line KYSE150, we found that overexpression of NKAIN4 suppresses the migration capacity of the cancer cells." (PMID 36509761, 2022).
lymph node metastasis (1 paper, 2022). "This study constructed a prognostic model of genes related to lymph node metastasis in COAD and found that PMCH, CD1B, NAT1, NKAIN4, and LRP2 have prognostic, predictive values." (PMID 36727052, 2022). "The high expression of NKAIN4 and LRP2 is related to the poor prognosis of COAD patients and has a co-expression relationship with the immune infiltrating cells related to lymph node metastasis." (PMID 36727052, 2022).
mesothelioma (1 paper, 2011). A usually malignant and aggressive neoplasm of the mesothelium which is often associated with exposure to asbestos. "To confirm the specificity of these markers in human mesothelium and mesothelioma we designed primers against human MSLN, UPK3B, NKAIN4 and LRRN4 and tested their specificity by qRTPCR against a panel of 45 human total RNAs." (PMID 21984916, 2011).
cancer (3 papers, 2021 to 2022). A tumor composed of atypical neoplastic, often pleomorphic cells that invade other tissues. "We further validated the effects of a previously uncharacterized sodium/potassium-ATPase interacting protein NKAIN4 on cancer cell migration with wound healing assay." (PMID 36509761, 2022). "In addition, targeted drugs against LRP2 and NKAIN4 may also improve the immune tolerance of cancer cells, thereby reducing the proliferation, invasion and migration capabilities of cancer cells, and improving the prognosis of patients." (PMID 36727052, 2022).
tumor (2 papers, 2022). "We speculate that in COAD, NKAIN4 further promotes the activity and function of the sodium-potassium pump by activating the expression of the β1 subunit, thereby promoting tumor proliferation and progression." (PMID 36727052, 2022). "Low expression of FABP4 in tumor tissues (p < 0.05) was validated in five datasets, the lower expression of PLXNB3, INHBB and NKAIN4 in tumor tissues was verified in three datasets (p < 0.05), and the decreased expression of HOXC9 and was validated in one dataset, respectively (p < 0.05)." (PMID 35721480, 2022). "Furthermore, 30 clinical CRC tissues (including tumor tissues and the corresponding adjacent tumor tissues as well as normal tissues) were collected, and the expression of FABP4, HOXC9, INHBB, NKAIN4, and PLXNB3 was determined using RT-PCR." (PMID 35721480, 2022).
NKAIN4 also shares sentences with these, for which no sentence is quoted: cystic fibrosis (1 paper); ovarian carcinoma (1).